MIR4667 (microRNA 4667)
Synonyms: hsa-mir-4667; mir-4667
Gene: MicroRNA gene on chromosome 9 (35,608,094 to 35,608,159, forward strand). Ensembl gene ENSG00000263892.
Homologues: Orthologues: chimpanzee MIR4667 (100% identical).